EGR2 (early growth response 2)
Diseases named in the same sentence as EGR2 in open-access papers (continued):
Sharing a sentence is not in itself a finding about the gene and the disease.
schizophrenia (9 papers, 2014 to 2024). A major psychotic disorder characterized by abnormalities in the perception or expression of reality. "Mendelian randomization analysis shows evidence of potential causality between increased expression of EGR2 in the cortex and schizophrenia (OR = 1.21, 95% CI = (1.09,1.35), p.adj = 0.002)." (PMID 38383672, 2024). "Previous studies have shown that Egr2 is crucial for normal hindbrain development, peripheral myelination, and humoral immune response and is implicated in diseases such as congenital hypomyelinating neuropathy, Charcot–Marie-Tooth disease, Dejerine–Sottas syndrome, as well as schizophrenia." (PMID 33724178, 2021). "Of these, we defined 15 genes showing evidence of involvement in both type 2 diabetes and schizophrenia with a total score of at least three, and three putative effector genes that displayed at least four different lines of evidence, namely EGR2, LAMA4 and NUS1." (PMID 38383672, 2024). "In accordance, haloperidol, aripiprazole, and olanzapine robustly induced the transcription of c-fos, Arc, and Egr2, suggesting that the induction of these genes may be involved in improvement of positive symptoms of schizophrenia." (PMID 25693194, 2015). "Our data show that antipsychotics clinically effective in positive symptoms of schizophrenia, haloperidol, aripiprazole, and olanzapine have homologous temporal and spatial TFPs showing a transcriptional induction of c-fos, Arc, and Egr2, particularly in nucleus accumbens and striatum." (PMID 25693194, 2015). "In a mouse model of maternal influenza viral infection, which is a risk factor for schizophrenia, an adult-onset abnormal response to DOI is observed, with an exaggerated head-twitch response and expression of the genes c-fos, egr-1 and egr-2 in cortical neurons." (PMID 24586556, 2014). "Pathway analysis of the NeuN+ TFs affected by age in the AT-schizophrenia/control cohort led to the top pathway ‘NGF-simulated transcription’ (p-value 8.04×10–8), including the TFs EGR2 and ATF2." (PMID 38648100, 2024). "EGR3 interacts in regulatory feedback loops with other EGR-family genes in the immune system, including EGR1, EGR2, EGR4 and NAB2, each of which maps to GWAS loci for schizophrenia." (PMID 35941129, 2022). "We previously reported the genetic association of EGR3 with schizophrenia and downregulation of the transcripts for EGR1, EGR2, and EGR3 in the postmortem brain samples from patients with schizophrenia." (PMID 33656268, 2021). "Moreover, the downregulation of EGR1, EGR2, and EGR3 transcripts was reported in the postmortem brains of patients with schizophrenia." (PMID 39518903, 2024).
Anxiety (6 papers, 2014 to 2024). Intense feelings of nervousness, tension, or panic often arise in response to interpersonal stresses. "Through the PPI network we found that the potential targets of ZZCD for the treatment of anxiety and depression are Fos, Nr4a1, Dusp1, Junb, and Egr2." (PMID 37905694, 2024). "Among them, Dcc, Egr2, and Fos are the most crucial genes that are involved in anxiety-related biological processes and pathways, including the regulation of neuronal death and neuroinflammation." (PMID 36432096, 2022). "Fos and Egr2 have been reported to be activated in germ-free mice that have anxiety-related behavior and impaired social behavior." (PMID 31024236, 2019). "Among them, Dcc, Egr2, and Fos play an important role in anxiety-related biological processes and pathways, and our study indicates that the anxiolytic effects of CIEO could be mediated through the regulation of these genes." (PMID 36432096, 2022). "In respect to Egr2 this suggestion is supported by findings in Egr2-deficient mice that display no signs of locomotor, exploratory or anxiety disturbances." (PMID 24966820, 2014).
hepatocellular carcinoma (5 papers, 2020 to 2026). A malignant tumor that arises from hepatocytes. "In cancer, NFAT2 inhibits the growth of hepatocellular carcinoma by inducing EGR2 expression." (PMID 35971091, 2022). "Overexpression of NFAT2 could significantly restrain hepatocellular carcinoma progression through increasing Egr2 expression." (PMID 34130587, 2021). "In addition to human hepatoma cells lines, Egr2 is expressed in rat liver." (PMID 40505865, 2025). "The absence of NFAT2 and Egr2 in carcinoma tissues reminded us that NFAT2 may be a promising therapeutic target for hepatocellular carcinoma treatment." (PMID 33023539, 2020). "The mRNA and protein expression of NFAT2, Egr2, FasL, COX-2 and c-myc was examined in 20 pairs of hepatic carcinoma tissues and adjacent nontumor tissues." (PMID 33023539, 2020).
neuropathies (5 papers, 2018 to 2026). "For example, among the most consistent DEGs induced by THC was EGR2, which is associated with neuropathy and congenital hypomyelination of peripheral neurons." (PMID 41402937, 2025). "Advances in molecular genetics have identified key causative genes, including PMP22, MPZ, MFN2, TTR, EGR2, and CX32 (GJB1), which are implicated in Charcot–Marie–Tooth disease, Dejerine–Sottas syndrome, and related neuropathies." (PMID 41595476, 2026). "De novo dominant variants predicted to affect function have been well reported in association with early-onset neuropathies in PMP22, MPZ and EGR2 [20, 21,]." (PMID 29511323, 2018). "The phenotype is complicated by clinical features of white matter lesions and FMH which may be a chance association, although it would be important to consider the possibility of central nervous system involvement in future cases of EGR2-related neuropathies." (PMID 31852952, 2019).
cardiac hypertrophy (4 papers, 2017 to 2025). "HHQ16 also significantly inhibited ISO, Ang II or ISO + PE induced high expression of lnc9456 in the primary or HL-1 cardiomyocytes, implicating that the effects of HHQ16 on cardiac hypertrophy and HF is associated with a strong inhibition of a new Egr2-affiliated transcript lnc9456." (PMID 37857609, 2023). "As Egr1 and Egr3, two paralogous genes of Egr2, are both CV genes, and Egr2 is likely a CV gene and an essential regulator for TAB-induced cardiac hypertrophy." (PMID 28790436, 2017).
Ewing sarcoma (4 papers, 2013 to 2022). A small round cell tumor that lacks morphologic, immunohistochemical, and electron microscopic evidence of neuroectodermal differentiation. "A variant upstream of EGR2 has been associated in a GWAS of Ewings sarcoma." (PMID 23555315, 2013). "Recently published observations of a different frequency of SNPs variants of the EGR2 gene related to Ewing sarcoma susceptibility and may account for this observation, since the frequency of the SNP variant is significantly higher in the non-Africans than in patients of African origin." (PMID 27524931, 2016). "Also notable is a strong link between SNPs in EGR2 (ER- association) and risk of Ewing's sarcoma." (PMID 23555315, 2013). "Altogether, our data show that the activation of the mevalonate pathway in Ewing sarcoma is a direct consequence of the activation of EGR2 by EWSR1-FLI1 and that this pathway can be efficiently targeted by statins." (PMID 35565457, 2022). "The 10q21 variants strongly associated with Ewing's sarcoma are located in a block containing four genes: ADO (encoding cysteamine dioxygenase), ZNF365 (encoding zinc-finger protein 365), EGR2 (encoding early growth response protein 2) and LOC107984012 (unknown function)." (PMID 29719630, 2018).
Insulin resistance (4 papers, 2020 to 2024). Increased resistance towards insulin, that is, diminished effectiveness of insulin in reducing blood glucose levels. "Egr2 downregulation has been associated with a metabolic shift in a hepatocyte-derived cell line that improved glucose uptake and decreased altered lipid metabolism associated with insulin resistance." (PMID 35763355, 2022). "MEG3 aggravated palmitate-induced insulin resistance by regulating miR-185-5p/Egr2 axis as a ceRNA in insulin-resistant hepatocytes." (PMID 33224264, 2020). "Egr2 represses the expression of SOCS-1 and the phosphorylation of JAK2 and STAT3 in HepG2 cells following palmitate treatment, and Egr2 upregulation induces insulin resistance in HepG2 cells." (PMID 38396891, 2024).
lung adenocarcinoma (4 papers, 2017 to 2025). A carcinoma that arises from the lung and is characterized by the presence of malignant glandular epithelial cells. "As the functional roles of the two representative signature genes SLC16A3 and EGR2 in lung adenocarcinoma progression remain incompletely elucidated, we selected them for expression and functional validation using a series of in vitro assays." (PMID 41583466, 2025). "To investigate their biological functions, we separately performed SLC16A3 knockdown and EGR2 overexpression in lung adenocarcinoma cells, with transfection efficiency confirmed by Western blotting." (PMID 41583466, 2025). "Accordingly, EGR1, EGR2, and EGR3 were differentially expressed genes (DEGs) in several cancers, such as bladder urothelial carcinoma (BLCA), BRCA, and lung adenocarcinoma (LUAD)." (PMID 33614706, 2020). "By integrating two time-course microarray data in human lung adenocarcinoma cells, we specifically have identified some nested gene clusters and found that TGFB1, EGR1, EGR2, EGFR, IL6, JUN, and JUNB all are involved in these clusters." (PMID 28959347, 2017).
asthma (3 papers, 2020 to 2024). "YAP, HIF-1α, and miR-182 were upregulated but EGR2 was downregulated in human and mouse peripheral blood mononuclear cells from the asthma group." (PMID 33980319, 2021). "Abundant expression of YAP and HIF-1α promoted miR-182 expression and then inhibited EGR2, a target of miR-182, thus enhancing Th17 differentiation and deteriorating asthma and lipid metabolism dysfunction." (PMID 33980319, 2021). "In conclusion, the findings in the current study demonstrated that YAP/HIF-1α enhanced Th17 cell differentiation, consequently exacerbating asthma and lipid metabolism dysfunction via miR-182-mediated EGR2 inhibition." (PMID 33980319, 2021). "In general, further studies with different cell lines, different disease models, and larger cohorts are essential to validate the findings of the current study and validate the translational potential of the YAP/HIF-1α/miR-182/EGR2 signaling axis in asthma." (PMID 33980319, 2021). "Indirectly perturbed genes near ATF3 and EGR2 in the network include C2, SERPING1, ZG16B, and CEACAM3, all of which have been linked to immune response, asthma, or auto-immune diseases." (PMID 33095769, 2020). "Egr2 plays an important role in asthma by regulating Th17 cell differentiation." (PMID 38666929, 2024). "The results demonstrated that EGR2 expression was downregulated in asthma (p < 0.05)." (PMID 33980319, 2021). "In addition, in vivo overexpression of EGR2 countered the promoting effect of the YAP/HIF-1α/miR-182 axis on asthma and lipid metabolism dysfunction." (PMID 33980319, 2021). "Based on these results we validated the hypothesis that amplified EGR2 eliminated Th17 cell differentiation, asthma, and lipid metabolism dysfunction driven by YAP/HIF-1α/miR-182 signaling." (PMID 33980319, 2021). "EGR2 has been linked to migration of CD4+ T cells to lung and to blood eosinophil levels in asthma." (PMID 33095769, 2020). "Thus, the YAP/HIF-1α/miR-182/EGR2 signaling may serve as a novel biomarker for asthma diagnosis and prognosis." (PMID 33980319, 2021). "The aim of this study was to investigate if the Yes-associated protein (YAP)/hypoxia inducible factor-1α (HIF-1α)/microRNA-182 (miR-182)/early growth response 2 (EGR2) axis is involved in mediating Th17 cell differentiation and disease severity in asthma." (PMID 33980319, 2021). "Asthma mice presented with elevated YAP and HIF-1α expression, but reduced EGR2 expression (p < 0.05)." (PMID 33980319, 2021). "In addition, asthma mice treated with oe-YAP, oe-HIF-1α, or miR-182 mimic presented with reduced HDL-C levels, while increased HDL-C levels were found in response to EGR2 overexpression (p < 0.05)." (PMID 33980319, 2021).
bipolar disorder (3 papers, 2022 to 2024). A disorder of the brain that causes unusual shifts in mood, energy, activity levels and the ability to carry out day-to-day tasks. "EGR2 is involved in cognitive function and was reported to be a possible susceptibility gene for human bipolar disorder." (PMID 36835261, 2023). "In Korea, a link has been found between EGR2 and bipolar disorder." (PMID 36405016, 2022). "Additionally, a genetic link between EGR2 and EGR3 and bipolar disorder was recently identified." (PMID 39518903, 2024).
colorectal cancer (3 papers, 2023 to 2025). A primary or metastatic malignant neoplasm that affects the colon or rectum. "The increased activity of EGR2 (P < 1.00×10−278) facilitates the persistence of colorectal cancer stem cells." (PMID 40585960, 2025). "The percentage of Egr2 positive TILs varied greatly in different tumours with ~ 30% in TILs from colorectal cancer, ~ 15% in those from liver cancer and ~ 9% in TILs from lung cancer." (PMID 36342511, 2023). "The percentage of Egr2 positive CD8 + TILs also varied greatly among patients with the same cancer, ranging from 10% to more than 40% in individual colorectal cancer patients." (PMID 36342511, 2023). "To assess the functional pathways potentially regulated by Egr2, we performed Gene set enrichment analysis (GSEA) on pseudobulk samples formed from Egr2 high and Egr2 low cells from one data set from a cohort of colorectal cancer patients." (PMID 36342511, 2023).
COVID-19 (3 papers, 2023 to 2024). A disease caused by infection with severe acute respiratory syndrome coronavirus 2. "Results from the autopsy of lungs from obese COVID-19 patients showed upregulation of the lymphocyte-specific kinase (LCK) and early growth response 2 (EGR2) genes." (PMID 37408184, 2023). "The remaining 8 key genes (EGR2, HIST1H3H, HIST1H4H, HIST1H4I, HIST1H4K, MTHFD2, TUBA4A, and TUBB1) were less studied in the roles of COVID-19 and OA, emphasizing their importance in future research." (PMID 37291167, 2023).
diabetes (3 papers, 2010 to 2025). "These include transcription factors concerned with the control of: adipogenesis (Pparγ, Klf15, Irf1, Creb1, Egr2, Gata3); lipogenesis (Mlxipl, Srebp1c); inflammation (Jun, Stat3); insulin signalling and diabetes susceptibility (Foxo1, Tcf7l2)." (PMID 21187013, 2010). "EGR1 and EGR2 play a key role in insulin signaling and lipid metabolism and have been involved in adipocyte differentiation programs, and RREB1 has been shown as novel candidate gene for diabetes affecting insulin sensitivity, beta-cell function and adipogenesis." (PMID 40646607, 2025).
glioma (3 papers, 2018 to 2024). A benign or malignant brain and spinal cord tumor that arises from glial cells (astrocytes, oligodendrocytes, ependymal cells). "Furthermore, the authors found that high Egr2 and DGKα expression in NK cells infiltrating acute myeloid leukemia and glioma tumors was associated with significantly reduced patient survival compared to NK cells exhibiting low Egr2 and DGKα expression profiles." (PMID 38886578, 2024). "EGR2, one of the zinc‐finger transcription factors belonging to the family of early growth response genes, has been discovered to facilitate cell invasion in glioma." (PMID 36987665, 2023). "A prior publication reported that EGR2 knockdown curtailed cell invasion in glioma." (PMID 36987665, 2023).
heart failure (3 papers, 2021 to 2025). Inability of the heart to pump blood at an adequate rate to meet tissue metabolic requirements. "Through PPI network and logistic regression, we identified EGR1, EGR2, FOS and FOSB as potential diagnostic biomarkers and therapeutic targets for heart failure." (PMID 36859608, 2023). "Second, we identified EGR1, EGR2, FOS and FOSB as potential diagnostic biomarkers and therapeutic targets for heart failure." (PMID 36859608, 2023). "In addition, we identified EGR1, EGR2, FOS and FOSB as potential diagnostic biomarkers and therapeutic targets for heart failure." (PMID 36859608, 2023). "For the differential genes associated LMNA alone with euchromatin, we obtained 5 candidate genes (EGR2, NMB, CREBBP, PRF1, and TENM4), of which EGR2 and NMB have been reported to involve in myocardial ischemia and heart failure, respectively." (PMID 33407844, 2021).
melanoma (3 papers, 2023 to 2025). A malignant, usually aggressive tumor composed of atypical, neoplastic melanocytes. "In this work, we demonstrated a metamaterial-based biosensor that enables the specific detection of EGR2, a biomarker that is associated with epigenetic dysfunction in melanoma." (PMID 38001098, 2023). "Due to the resulting increased activity of EGR2 in melanoma, it is used as a biomarker within this work." (PMID 38001098, 2023). "Despite the restricted comparability of EGR2 mRNA abundance and the resulting protein activity, this proportion allows an approximation of the EGR2 amount in melanoma cells and highlights the degree of selectivity and sensitivity of the proposed sensor." (PMID 38001098, 2023). "Similarly, significant upregulation of CD163 and EGR2 highlights the polarised state of macrophages towards an M2 phenotype in melanoma samples." (PMID 40134439, 2025). "Egr2 and Egr3 can induce the expression of Nab2 in melanoma cells." (PMID 38666929, 2024). "In this work, we present a highly selective and sensitive biosensor for melanoma diagnosis capable of specific EGR2 detection from a complex sample matrix directly derived from complete melanoma cell nuclei (containing approximately 7000 different protein species)." (PMID 38001098, 2023).
myocardial infarction (3 papers, 2021 to 2022). Gross necrosis of the myocardium, as a result of interruption of the blood supply to the area, as in coronary thrombosis. "A recent study showed that the inhibition of long non-coding RNA MIAT ameliorates myocardial dysfunction induced by myocardial infarction via MIAT/miR-10a-5p/EGR2 axis." (PMID 35971091, 2022). "In comparison with the Ad-sh-MIAT injection group, the myocardial infarct size was significantly increased when the mice were injected with both Ad-sh-MIAT and oe-EGR2." (PMID 33819189, 2021).
prostate carcinoma (3 papers, 2020 to 2023). A carcinoma that arises from epithelial cells of the prostate gland. "For instance, the methylation of the first intron of the EGR2 gene, known as a tumor suppressor, affects the recruitment of proteins required for transcription, and anti-tumorigenic PMP24 gene is silenced by the intronic single CpG methylation in prostate cancer cells." (PMID 32693820, 2020).
Stroke (3 papers, 2024 to 2026). Sudden impairment of blood flow to a part of the brain due to occlusion or rupture of an artery to the brain. "Mengozzi discovered that EGR2 and EGR4 were upregulated by neuroprotective erythropoietin in a model of middle cerebral artery occlusion, and this regulation was validated in stroke-related experiments, highlighting their association with ischemia." (PMID 38166990, 2024).